RIPK3 (receptor interacting serine/threonine kinase 3)
Diseases named in the same sentence as RIPK3 in open-access papers (continued):
Sharing a sentence is not in itself a finding about the gene and the disease.
pancreatic cancer (19 papers, 2016 to 2025). "Using a RIPK3 rescue model in a RIPK3-deficient pancreatic cancer cell line which normally cannot undergo necroptosis, we demonstrate that the evolutionary conserved dimethylated arginine residue R486 is important for RIPK3-mediated feedback control on RIPK1 autophosphorylation." (PMID 36658119, 2023). "A mouse model, used for the investigation of pancreatic cancer, showed that the depletion of RIPK3 led to the formation of a suppressive TIME, which promoted tumorigenesis." (PMID 39858052, 2025). "RIPK3/RIPK1 regulation of CXCL1 in pancreatic cancer restricts infiltration of highly immunogenic T or B cells to promote tumor migration and invasion." (PMID 35965497, 2022). "A mouse model of pancreatic cancer showed that knocking out RIPK3 or RIPK1 inhibited oncogenic progression." (PMID 35725836, 2022). "RIPK1 and RIPK3 can induce necroptosis to drive pancreatic cancer progression." (PMID 37016317, 2023). "In pancreatic cancer, its overexpression accelerates tumor progression by inhibiting necroptosis through the RIPK1/RIPK3/MLKL signaling cascade." (PMID 41180485, 2025). "In pancreatic cancer, CHMP4C facilitates progression by inhibiting necroptosis via the RIPK1/RIPK3/MLKL pathway, thereby emphasizing its role in cell survival and proliferation." (PMID 40893939, 2025). "At the same time, the upregulation of RIPK3 or RIPK1 is involved in the occurrence and progression of glioma, pulmonary carcinoma, and pancreatic cancer." (PMID 37580654, 2023). "To monitor RIPK3 functions and to investigate the significance of RIPK3 methylation, we established a rescue model of RIPK3 activity using the PANC1 human pancreatic cancer cell line." (PMID 36658119, 2023). "The aurora kinase inhibitor, CCT137690, triggered the necroptosis of pancreatic cancer cells by RIPK1, RIPK3, and MLKL, and hindered the growth of in situ pancreatic tumors in mice." (PMID 36981005, 2023). "Despite IMB5036′s ability to partially activate apoptosis and pyroptosis, its primary mode of action is necroptosis, initiated by the upregulation of RIPK1, RIPK3, and largely MLKL in pancreatic cancer cells." (PMID 37893166, 2023). "RIPK3 and MLKL were also found increased in human pancreatic cancer tissues compared with normal pancreas, which promote pancreatic cancer cell migration and invasion." (PMID 39872161, 2022). "In contrast, it is reported that RIPK1 and RIPK3 are overexpressed in pancreatic cancer tissues, and downregulation of RIPK1 or deletion of RIPK3 in vivo inhibited tumor progression via enhancing immune cell infiltration." (PMID 35756487, 2022). "In addition, another anti-diabetic drug, the Vanadium compound, triggered various cell death in pancreatic cancer by inhibiting the cell cycle, increasing ROS, and upregulating RIPK1 and RIPK3 in a dose-dependent manner." (PMID 37893166, 2023).
systemic inflammatory response syndrome (19 papers, 2014 to 2024). SIRS is a serious condition related to systemic inflammation, organ dysfunction, and organ failure. "Nec-1 treatment or RIPK3 deficiency also protected against TNF-α induced systemic inflammatory response syndrome (SIRS)." (PMID 37935670, 2023). "In turn, loss of MLKL or RIPK3 protected mice from TNF‐induced systemic inflammatory response syndrome (SIRS)." (PMID 33314666, 2020). "TNF-induced systemic inflammatory response syndrome (SIRS) is the most used models for proving the roles in necroptosis as RIPK3 or MLKL KO mice are resistant." (PMID 35217652, 2022). "Type I IFNs drive receptor interacting serine/threonine protein kinase 3 (RIPK3)-dependent macrophage necroptosis in Salmonella typhimurium infection, and are required for TNFα-induced systemic inflammatory response syndrome, wherein RIPK3 drives pathology." (PMID 30080899, 2018). "In a mouse model of systemic inflammatory response syndrome (SIRS), the combined loss of MLKL (or RIPK3) and caspase-8 provides significant protection, suggesting that necroptosis and apoptosis coexist in the inflammation mechanism." (PMID 34594225, 2021). "Nevertheless, both approaches indicate that RIPK1/RIPK3-mediated cellular damage by necrosis drives mortality during TNFα-induced systemic inflammatory response syndrome (SIRS)." (PMID 27048815, 2016). "Moreover, mice with kinase-dead RIPK1 knock-in mutations are resistant to TNF-induced necroptosis and systemic inflammatory response syndrome (SIRS), similar to RIPK3 knockout mice, and demonstrate superior resistance compared to MLKL knockout mice." (PMID 39062098, 2024). "To demonstrate scalability, we used automated immunohistochemistry to characterize the expression of Caspase-8, RIPK1 and RIPK3 across six tissues during TNF-induced systemic inflammatory response syndrome (SIRS)—a widely-used model of RIPK-dependent pathology." (PMID 38750308, 2024). "Necroptosis has been reported to drive systemic inflammatory response syndrome (SIRS), while necroptosis inhibition by genetic means (e.g., deletion in RIPK3 gene) or by pharmacological means (RIPK1 inhibition by necrostatin-1) protects against SIRS." (PMID 36611990, 2023). "We then identified Ibrutinib as an inhibitor of RIPK3 and found that Quizartinib protected against the TNF-induced systemic inflammatory response syndrome in mice by inhibiting the activation of RIPK1." (PMID 37741898, 2023). "In RIPK1- and RIPK3-dependent processes, necroptosis mediates TNF-induced systemic inflammatory response syndrome." (PMID 32366830, 2020). "In addition, in vitro assays with purified proteins showed that CK1γ phosphorylated RIPK3, affecting its activity, and in vivo assays showed that the CK1γ-specific inhibitor Gi prevented abrupt death in mice with hypothermia in a model of TNFα-induced systemic inflammatory response syndrome." (PMID 31801942, 2019). "Studies on mouse models have also shown that TNF-induced systemic inflammatory response syndrome (SIRS) and CLP-induced peritoneal sepsis are driven by both RIPK1 and RIPK3-dependent necroptosis." (PMID 26491219, 2015). "Several type II kinase inhibitors such as the FDA approved drugs ponatinib and sorafenib, which target RIPK1, also block the kinase activity of RIPK3 and can protect mice from TNF-induced systemic inflammatory response syndrome (SIRS) and renal ischemia-reperfusion injury." (PMID 37409125, 2023). "Studies on mouse models of the TNF-induced systemic inflammatory response syndrome (SIRS) and CLP-induced peritoneal sepsis have shown that multiple organ failure and animal mortality are driven by both RIPK1 and RIPK3-dependent necroptosis." (PMID 25140116, 2014).
glioma (17 papers, 2014 to 2025). A benign or malignant brain and spinal cord tumor that arises from glial cells (astrocytes, oligodendrocytes, ependymal cells). "The authors conclude that impaired necroptosis due to αHG-mediated promoter hypermethylation of RIPK3 is an important mechanism in the tumor development of IDH-mutated gliomas." (PMID 39062119, 2024). "ZZW-115, an antitumor agent that triggers both apoptosis and necroptosis, and citronellol, a natural compound that promotes RIPK1/RIPK3-dependent necroptosis, were tested in U251 and U87 glioma lines." (PMID 41429922, 2025). "Analysis of The Cancer Genome Atlas (TCGA) and Genotype-Tissue Expression (GTEx) databases revealed a significant upregulation of RIPK1 and RIPK3 mRNAs in grade II–IV gliomas (G2–G4) compared with normal brain tissue." (PMID 41429922, 2025). "Collectively, these data highlight the association between necroptosis machinery and glioma aggressiveness, suggesting a pivotal role for RIPK1, RIPK3, and MLKL in disease progression and clinical outcome." (PMID 41429922, 2025). "A Cox proportional hazards model applied to 23 TCGA cancer cohorts identified RIPK1, RIPK3, and MLKL as significant risk factors for OS in WHO grade II and III gliomas." (PMID 41429922, 2025). "αHG also contributes to promoter methylation of the gene for RIPK3, leading to reduced RIPK3 expression and inhibition of necroptosis of glioma cells." (PMID 39062119, 2024). "Among the seven prognostic necroptosis genes, especially RIPK1, RIPK3, FAS and FADD, can construct risk profiles and predict the prognosis of glioma patients." (PMID 38304870, 2024). "Of the seven prognostic necroptosis genes, RIPK1, RIPK3, FAS, and FADD were used to construct the risk signature that accurately predicts the prognosis of glioma patients." (PMID 35719998, 2022). "To validate these findings, we performed Western blot analyses across a clinical cohort of 81 glioma samples (16 grade II, 19 grade III, and 46 grade IV), which revealed significant upregulation of RIPK1 and MLKL and downregulation of RIPK3 in grade IV tumors relative to lower-grade gliomas." (PMID 41429922, 2025). "Consistently, two vital effector molecules, RIPK1 and RIPK3 were also highly expressed in glioma, suggesting that initiation of necroptosis may be critically regulated by these highly expressed upstream NRGs in glioma." (PMID 36466844, 2022). "The risk scores of glioma patients were calculated based on the coefficient and expression levels of each gene and the formula was as follows: risk score = 0.431 * RIPK1 +0.227 * RIPK3 + 0.302 * FAS +0.373 *FADD." (PMID 35719998, 2022). "While necroptosis competency has been reported in glioma, such cases might be rare, since RIPK3 expression is frequently epigenetically silenced." (PMID 34168123, 2021). "Interestingly, in mutant as well as non-mutant gliomas, RIPK3 expression can additionally stratify the risk of patients: high RIPK3 expression is correlated with a worse prognosis contrasting to most other entities." (PMID 39858052, 2025). "Together, these findings demonstrate that the necroptotic genes RIPK1, RIPK3, and MLKL are robust predictors of adverse clinical outcomes across glioma subtypes." (PMID 41429922, 2025). "In both TCGA and CGGA cohorts, tumors with wild-type IDH exhibited higher expression of RIPK1, RIPK3, and MLKL relative to IDH-mutant gliomas, consistent with the more aggressive clinical behavior associated with IDH-wild-type status." (PMID 41429922, 2025). "Here, we integrate analyses of RIPK1, RIPK3, and MLKL across clinical glioma samples and experimental models to define the contribution of the necroptotic pathway to glioma pathobiology." (PMID 41429922, 2025). "In this study, we demonstrate that the necroptotic machinery genes RIPK1, RIPK3, and MLKL are highly expressed in gliomas and positively correlate with disease progression and patient prognosis." (PMID 41429922, 2025).
glioma (continued). "Similar findings were observed in the CGGA dataset, where RIPK1, RIPK3, and MLKL served as independent prognostic indicators across all WHO grades and within grade III gliomas." (PMID 41429922, 2025). "To assess the prognostic significance of the necroptotic genes RIPK1, RIPK3, and MLKL in gliomas, we performed survival analyses across multiple datasets." (PMID 41429922, 2025). "To investigate the role of the necroptotic machinery in glioma, we analyzed the mRNA expression profiles of RIPK1, RIPK3, and MLKL across normal brain and glioma samples." (PMID 41429922, 2025). "Similar results were observed in the Chinese Glioma Genome Atlas (CGGA) dataset, where mRNA levels of RIPK1, RIPK3, and MLKL were elevated across glioma grades." (PMID 41429922, 2025). "As expected, increased expression in gliomas has also been observed for TNF-α, TNFR1, RIPK1, and RIPK3." (PMID 39062119, 2024). "Compared with normal tissues, except for MEFV, NLRP6, NLRP9, RIPK3, and ZBP1, the expression levels of the remaining genes were relatively high in glioma tissues." (PMID 37501725, 2023). "As shown by the bean plot, 7 genes (RIPK1, RIPK3, FAS, FADD, FASLG, TLR3, and TNF) were upregulated in the glioma tissues with p <0.001." (PMID 35719998, 2022). "Glioma cells were treated with CBD and GSK872 (1 μM), a RIPK3 inhibitor and putative inhibitor of necroptosis." (PMID 34456736, 2021). "In a rat glioma model, apoptosis was induced by activation of CASP8 and inhibition of RIPK1/RIPK3 complex." (PMID 29912993, 2018). "Two important examples are the plant-derived flavonoid, kaempferol, which leads to induction of autophagy and pyroptosis of glioma cells, and the plant-derived cytokine N6-isopentenyladenosine (iPA), which leads to activation of RIPK1, RIPK3, and MLDL, with subsequent induction of necroptosis." (PMID 39062119, 2024). "We observed an upregulation of programed necrosis-related proteins MLKL/RIPK3 and a concomitant downregulation of RIPK1 expression in glioma cell lines U251, U87, A172, and T98G, as well as in an in vivo subcutaneous tumor model, following Shikonin interventions." (PMID 39619148, 2024). "Of the NRGs, seven genes showed a significant difference between normal tissues and glioma, while RIPK3 did not." (PMID 37351504, 2023). "The high expression of TLR3 in lower grade glioma (LGG) and LUSC; FASLG in LGG, UVM, KIRC, and THYM; RIPK3 in LGG, KIRC, and LUSC; RIPK1 in LGG and THCA; FAS in LGG, UVM, and THYM; MLKL in LGG, UVM, and LUAD; FADD in LGG and HNSC; and TNF in UVM and CESC was associated with poor survival." (PMID 35748782, 2022). "In the glioma tumor cells, iPA led to the activation of RIPK1, RIPK3, and MLDL, but there was no activation of caspases." (PMID 39062119, 2024).
lung carcinoma (17 papers, 2016 to 2025). "Decreased expression of RIPK3 or MLKL was found to be associated with worse disease free survival of lung cancer." (PMID 35871768, 2022). "In lung cancer patients, an expression signature with low CHIP expression and high RIPK3 expression is associated with bad prognosis." (PMID 36658119, 2023). "Taken together, these results suggest that acetylshikonin activates the necroptosis pathway via the RIPK1/RIPK3/MLKL axis in lung cancer cells." (PMID 38126996, 2023). "In lung cancer, favorable DFS has been associated with RIPK3 IHC expression in lung adenocarcinoma patients who underwent adjuvant chemotherapy." (PMID 32521727, 2020). "In contrast to the clinical expression of RIPK3, high expression of RIPK1 in patients with lung cancer or pancreatic ductal adenocarcinoma is highly associated with poor prognosis." (PMID 33348858, 2020). "For instance, combining RIPK3 inhibitors with ferroptosis inducers could reduce inflammation while promoting tumor cell death in lung cancer patients." (PMID 39759427, 2025). "Moreover, upregulating RIPK3 expression can enhance the sensitivity of colon cancer cells to 5-FU and lung cancer cells to DDP through mediating necroptosis." (PMID 38239395, 2023). "Thus, RIPK3-mediated necroptosis pathway may be suppressed in lung cancer cells and lose its antitumor function." (PMID 34594225, 2021). "Increased phosphorylation of RIPK1/RIPK3 and MLKL activity indicates that acetylshikonin promoted necroptosis in lung cancer cells." (PMID 38126996, 2023). "RIPK3 inhibitors could be particularly valuable in diseases where necroptosis plays a significant role, such as COPD and certain types of lung cancer." (PMID 39759427, 2025). "On the other hand, there is also evidence that necroptosis may promote carcinogenesis by inducing adaptive immunosuppression; for instance, RIPK1 is overexpressed in glioblastoma, lung cancer, and pancreatic ductal adenocarcinoma (PDAC), and RIPK3 and MLKL are highly expressed in PDAC." (PMID 35769473, 2022). "On the other hand, it was reported that necroptosis could be mediated by MLKL but independent of RIPK1/RIPK3 signaling in transhinol A-stimulated lung cancer cells." (PMID 36030201, 2022). "Our study reported the prognostic significance of RIPK3 expression in the general population of lung cancer patients regardless of adjuvant therapy in contrast to a previous study that reported the prognostic value of RIPK3 in a specific subgroup of patients who had received adjuvant chemotherapy." (PMID 32521727, 2020).
cervical carcinoma (15 papers, 2015 to 2024). A carcinoma arising from either the exocervical squamous epithelium or the endocervical glandular epithelium. "Human cervical carcinoma cells (HeLa), deficient in RIPK3 expression, were used to investigate the role of RIPK3 in SpvB-mediated cell death." (PMID 35110556, 2022). "Our findings support this, showing a positive correlation between HSP90 expression and RIPK1 and RIPK3 in cervical cancer." (PMID 38338850, 2024). "Simultaneous expression of RIPK1 and RIPK3 in the nucleus is an independent positive prognosticator for OS and PFS further underlining a potential positive effect of necroptosis in cervical cancer patients." (PMID 37197430, 2023). "Nuclear RIPK3 expression was significantly higher in cervical cancer tissue with low grading (G1) compared to grading G2 and G3 (p = 0.011)." (PMID 37197430, 2023). "Aim of this study was the analysis of the expression of RIPK1, RIPK3 and pMLKL in cervical cancer tissue and the evaluation of its prognostic value on overall survival, progression-free survival and additional clinical parameters." (PMID 37197430, 2023). "Immunohistochemical staining showed that RIPK1 and pMLKL were expressed in the nucleus and cytoplasm while RIPK3 was expressed in the nucleus in cervical cancer tissue." (PMID 37197430, 2023). "Aim of this study was to analyze the expression of RIPK1, RIPK3, and pMLKL in cervical carcinoma patient tissue and to correlate their expression with clinical parameters, overall survival (OS) and progression-free survival (PFS)." (PMID 37197430, 2023). "Multivariate Cox regression analysis of cervical cancer patients (n = 250) and their clinical and pathological characteristics including nuclear RIPK3 expression regarding PFS." (PMID 37197430, 2023). "Spearman’s rank correlation coefficient was evaluated for RIPK1, RIPK3, pMLKL and various histopathological markers which were stained and analyzed in the applied cervical cancer patient collective of previous studies." (PMID 37197430, 2023). "Multivariate Cox regression analysis of cervical cancer patients (n = 250) and their clinical and pathological characteristics including nuclear RIPK3 expression regarding OS." (PMID 37197430, 2023). "In another multivariate Cox regression analysis, co-expression of nuclear RIPK1, nuclear RIPK3 and cytoplasmic pMLKL presented as a significant independent prognosticator for OS in cervical cancer patients." (PMID 37197430, 2023). "In conclusion, RIPK1 and RIPK3 are independent positive predictors for overall survival and progression-free survival in cervical cancer patients." (PMID 37197430, 2023). "The expression of RIPK1, RIPK3, and pMLKL in cervical cancer tissue microarrays of n = 250 patients was analyzed immunohistochemically." (PMID 37197430, 2023). "Even if this scenario suggests a protective role of RIPK3 against tumorigenesis, in cervical cancer, elevated expression of RIPK3 is detected." (PMID 35682876, 2022). "Our results confirmed that AL promoted upregulation of RIPK3 expression in cervical cancer HeLa cells and enhanced phosphorylation level of MLKL, which was reversed in the presence of bafilomycin A1 (BafA1)." (PMID 33927214, 2021). "Polyinosinic:polycytidylic acid (PolyI:C), which is a viral dsRNA analog, was reported to trigger necroptosis in cervical cancer, which strictly depended on the expression of RIPK3." (PMID 31122251, 2019). "In summary, our study has identified a novel RIPK3- and IL-1α-dependent mechanism that links dsRNA treatment of cervical cancer cells with DC activation." (PMID 25888634, 2015). "This study identified an unexpected role for receptor-interacting protein kinase 3 (RIPK3), a key regulator of necroptosis, as a critical determinant of the capacity of PolyIC-stimulated cervical cancer to enhance DC activation." (PMID 25888634, 2015).